RUNX1 (RUNX family transcription factor 1)
Diseases named in the same sentence as RUNX1 in open-access papers (continued):
Sharing a sentence is not in itself a finding about the gene and the disease.
glioma (45 papers, 2010 to 2026). A benign or malignant brain and spinal cord tumor that arises from glial cells (astrocytes, oligodendrocytes, ependymal cells). "In epithelial ovarian carcinoma 8, clear cell renal cell carcinoma 9, glioma 10, gastric cancer 11, and pancreatic cancer 12, RUNX1 has been linked to tumor progression." (PMID 39309442, 2024). "In central nervous system tumors, RUNX1 has been linked to the Mes state of GBM, in which it maintains the tumor initiating capacity and the ability of tumor cells to invade into the normal tissue." (PMID 31754093, 2019). "First, silencing of RUNX1 inhibited proliferation of glioma cell lines and increased the number of apoptotic cells in a manner similar to Chb-M′." (PMID 36085167, 2022). "Genes associated with the neuronal differentiation pathway (Pcsk9, Runx1, Cebpb, Fzd4, Wnt7a, Ascl1, Fzd2, Edn3, Olig2, and Gpc2), gliomas (Shc1, Cdk4, E2f2, and Ccnd1), and cell cycle (Bub1b, Bub, Ccnb1, Ccnb2, and Cdc20) were significantly downregulated." (PMID 36147849, 2022). "RUNX1 expression was significantly higher in primary glioblastomas than in normal tissue or grade 2 low-grade glioma (p < 0.0001)." (PMID 36085167, 2022). "Glioma patients with RUNX1 or REXO2 hypo-methylation had worse clinical outcomes than LGG patients with RUNX1 or REXO2 hyper-methylation in TCGA dataset." (PMID 34088969, 2021). "We found that RUNX1 highly expressed glioma had lower overall survival than RUNX1 lowly expressed glioma patients in TCGA (P < 0.0001) and CGGA (P < 0.0001) datasets." (PMID 34088969, 2021). "In tumors of the central nervous system, RUNX1 expression is significantly higher in Mesenchymal (Mes) subtype of GBM and closely related to Mes subtype initiation through microRNA (miR)-mediated mechanisms." (PMID 34895074, 2021). "Oncogenic RUNX1 promoted the growth of glioma cells as well as the expression of HCP5 and its binding to the tumor suppressor miRNA-139." (PMID 32375397, 2020). "A RUNX1-microRNA-139-HCP5 axis shows a positive FBL for mediating the tumor-suppressive effects of glioma cells." (PMID 32102656, 2020). "Analyses of The Cancer Genome Atlas (TCGA) and Chinese Glioma Genome Atlas (CGGA) verified the expression levels and prognoses associated with RUNX1/p-SMAD3/SUV39H1 target genes." (PMID 31754093, 2019). "RUNX1 down-regulation by knockdown using miR-139 as an inhibitor had the opposite effect on apoptosis and exerted tumor-suppressive effects in human glioma cells." (PMID 31137555, 2019). "For example, HCP5 enhances the biological behaviors of glioma cells by upregulating RUNX1, while RUNX1 also activates HCP5 expression through binding to its promoter region, forming a positive feedback loop." (PMID 31186064, 2019). "RUNX1 is a major regulator of the glioma mesenchymal subtype, and was found to interact with STAT3 in the miRNA-mediated RNA-RNA interaction network; it is therefore not unexpected that RUNX1 expression was downregulated by blocking the activity of STAT3." (PMID 25007077, 2014). "Additionally, patients with low-grade gliomas with high expression levels of RUNX1 and/or IFNGR2 have a worse prognosis, with a significant increase in the infiltration of M2 macrophages." (PMID 38430423, 2024). "Our finding indicated that RUNX1 could potentially promote glioma proliferation and migration by up-regulating the expression of CD44." (PMID 36776876, 2023). "The RUNX1/CD44 axis in gliomas remained valuable for further exploration." (PMID 36776876, 2023). "TTN-AS1 and SNHG1 are lncRNAs that promote glioma development by upregulating RUNX1." (PMID 35676651, 2022). "The phosphorylation of ERK Ser-249 and Ser-266 phosphorylation might affect the occurrence of glioma through Aml1/Runx1." (PMID 36463205, 2022).
glioma (continued). "We examined microarray data of GSE111260 again and found that BIRC5 was highly expressed in grade 4 glioma, along with RUNX1 (p < 0.0001), supporting the possibility that high BIRC5 expression may contribute to a higher grade of malignancy." (PMID 36085167, 2022). "We further tested the prognostic significance of RUNX1 in glioma patients." (PMID 34088969, 2021). "Furthermore, RUNX1 was further over-expressed in grade IV glioma (GBM) patients in TCGA (P = 1.8E−18) and CGGA (P = 0.002) datasets, suggested the increased expressions of RUNX1 with the increased malignance of glioma." (PMID 34088969, 2021). "Moreover, RUNX1 expression and methylation were correlated with IDH mutation and the clinical outcomes of LGG or glioma patients." (PMID 34088969, 2021). "Recent report shows that RUNX1 may be a putative molecular target of therapies against glioma metastasis and angiogenesis through the activation of p38 MAPK signaling pathway." (PMID 32319515, 2020). "In addition, RUNX1 is considered to a key factor participating in the malignant biological behavior of glioma cells." (PMID 33323543, 2020). "Recent report shows that RUNX1 may be a putative molecular target of therapies against glioma metastasis and angiogenesis that function through the activation of the p38 MAPK signaling pathway." (PMID 32319515, 2020). "The malignant behavior of glioma cells in the brain appears to be regulated by an HCP5–miR-139–RUNX1 feedback loop, whereby RUNX1 increased the promoter activities and expression of HCP5 that binds to the tumor suppressor miRNA-139 (miR-139) and, therefore, acts as an oncogene." (PMID 31137555, 2019). "Upregulated RUNX1 also inhibited apoptosis in glioma cell-lines U87 and U251." (PMID 31137555, 2019). "In addition, they found that HCP5 regulated the glioma cells malignant proliferation through binding to miR-139 by up-regulating RUNX1." (PMID 30364292, 2018). "In GBM, knockdown of RUNX1 in U-87 MG cells inhibits the angiogenesis of human umbilical vein endothelial cells, and a p38 MAPK inhibitor (SB203580) reduces RUNX1 expression levels; thus, RUNX1 may promote angiogenesis in gliomas through activation of the p38 MAPK signaling pathway." (PMID 38430423, 2024). "However, RUNX1 has not been shown to carry any pathogenic mutation effects on gliomas, suggesting its distinctive critical roles in gliomas." (PMID 38286983, 2024). "However, the prognosis of RUNX1 in lower grade glioma (LGG), particularly in IDH wild type LGG was unknown." (PMID 34088969, 2021). "To investigate whether the RUNX1 has mutation in tumor tissues, we examined TCGA pancancer genomic alterations and found no RUNX1 mutations in the investigated gliomas." (PMID 31754093, 2019). "The interaction of Circ-VPS18 with miR-370 downregulates runt-related transcription factor 1 (RUNX1) expression, a member of the RUNX transcription factors with oncogenic properties, and subsequently accelerates the glioma growth as well as TMZ-resistance." (PMID 39877636, 2025). "Elevated expression levels of both RUNX1 and its downstream target, REXO2, in isocitrate dehydrogenase wild-type low-grade gliomas are indicative of unfavorable prognosis." (PMID 38430423, 2024). "Next, we interrogated the glioma cohorts from TCGA and CGGA databases to further examine the expression and correlation characteristics of RUNX1, FOSL2, FN1, COL4A1, and LUM in GBM tumorigenesis." (PMID 38286983, 2024). "Further evidence of this is observed in the heightened expression levels of RUNX1 and its downstream target, REXO2, in isocitrate dehydrogenase wild-type low-grade gliomas, indicative of a poor prognosis." (PMID 39309442, 2024). "An important example is the investigation of activators of the JAK/Stat pathway such as Runx1 and VPS25, which are overexpressed in glioma tissues and thus serve as potential therapeutic targets." (PMID 37626776, 2023).
glioma (continued). "RUNX1 contributes the migration, invasion, angiogenesis and MES subtype of GBM, and is related to the prognosis of glioma patients." (PMID 36949071, 2023). "To determine expression levels of RUNX1 in glioblastoma tissues, we analysed GSE111260 microarray data set in comparison with normal brain and low-grade glioma tissue." (PMID 36085167, 2022). "HCP5 up-regulates runt-related transcription factor 1 (RUNX1) by acting as miR-139 sponge to promote astrocyte elevated gene-1 (AEG-1) expression, which is involved in several oncogenic effects in glioma cells." (PMID 33439936, 2021). "It has also been reported that the downregulation of RUNX1 restores TMZ sensitivity and inhibits glioma progression." (PMID 34895074, 2021). "The “sponging” effect of HCP5 on miRNA-139 unleashed the RUNX1 expression, connecting HCP5 to glioma oncogenesis." (PMID 32375397, 2020). "A subset of 7 transcription factors (STAT3, BHLHE40, CEBPA and B, RUNX1, FOSL2 and ZNF238) controlled most genes of the mesenchymal signature of gliomas; all but ZNF238 were significantly upregulated in the group 2 tumours compared to the other DIPG." (PMID 22389665, 2012). "The prognostic signature based on the expression profiles of RUNX1, FOSL2, and other ECM-related genes could be effectively utilized in predicting the prognosis and OS of glioma patients." (PMID 38286983, 2024). "By analyzing available public GBM datasets from the Cancer Genome Atlas (TCGA) and the Chinese Glioma Genome Atlas (CGGA), we revealed that FOSL2 was highly expressed in mesenchymal GBM, which was consistent with the expression characteristics of RUNX1." (PMID 38286983, 2024). "Further cell experiments revealed that RUNX1 could regulate the transcription and expression of IFNGR2 as well as participate in glioma cell proliferation, cycle, apoptosis, invasion, and migration, which may be realized through the IL2-STAT5 pathway." (PMID 36321611, 2023). "Subsequent results confirmed that RUNX1, as an independent prognostic factor for LGG, may target interferon-gamma receptor 2 (IFNGR2) to regulate glioma cell proliferation, invasion, and migration." (PMID 36321611, 2023). "We also found that RUNX1 can regulate the transcription and expression of IFNGR2 and is involved in the regulation of glioma cell proliferation, cycle, apoptosis, invasion, and migration, and the differentiation process of glioma mutant subtypes." (PMID 36321611, 2023). "The independent prognostic value of RUNX1, RUNX2, and RUNX3 in LGG was analyzed by Multivariate Cox regression analysis and then further verified with reference to the specific data of The Cancer Genome Atlas (TCGA) and Chinese Glioma Genome Atlas (CGGA)." (PMID 36321611, 2023). "This suggests that among the TFs previously characterized (such as FOSL2, STAT3, BHLHB2, and RUNX1), FOSL1 and CEBPB might play a dominant role in the NF1-mediated MES transition that occurs in a glioma cell-intrinsic manner." (PMID 34399888, 2021). "RUNX1 and REXO2 were further hypo-methylated in grade IV glioma (GBM) patients in TCGA dataset." (PMID 34088969, 2021). "In glioma, the expression of BRCA1, RUNX1, and SERPINE1 were analyzed using GSEA." (PMID 33723286, 2021). "A miR-18a-RUNX1-ZO-1 regulatory network also increases the permeability of the blood-tumor barrier (BTB), thereby providing novel potential targets for drug transportation across the BTB as an attractive strategy for glioma treatment." (PMID 32102656, 2020). "The HCP5 promoter also contains a 22 nt RUNX1 sequence that might contribute to the interaction between the HCP5 transcript and the Runx transcription factor in glioma and in the monocytes of HIV patients." (PMID 31137555, 2019). "RUNX1 and RUNX2 upregulate LGALS3 (galectin-3), a protein which suppresses anoikis and drug-induced apoptosis and whose expression is correlated with metastasis in osteosarcoma and progression in glioma." (PMID 20465837, 2010).
glioma (continued). "Besides, RUNX1/CD44 axis critically mediated the proliferation and migration of gliomas." (PMID 36776876, 2023). "Furthermore, RUNX1 and REXO2 were correlated with the worse prognosis of LGG or glioma." (PMID 34088969, 2021). "Furthermore, lncRNA HCP5 sponge miR-139 to up-regulate RUNX1, and then RUNX1 feedback promoted HCP5 expression by binding to HCP5 promoters, creating a HCP5/miR-139/RUNX1 positive feedback loop to regulate the malignant behavior of glioma cells." (PMID 29458374, 2018). "Finally, RUNX1/CD44 axis could promote the proliferation and migration of gliomas." (PMID 36776876, 2023).
gastric cancer (38 papers, 2014 to 2025). A primary or metastatic malignant neoplasm involving the stomach. "Existing studies have found that RUNX1 exerts a tumor suppressor effect in liver cancer and gastric cancer, but in non-small-cell lung cancer and endometrial cancer." (PMID 35498539, 2022). "Meanwhile, RUNX1 expression was decreased in multiple datasets, including adipose cancer, bone cancer, endometrium cancer, head and neck cancer, prostate cancer, and stomach cancer (all P < 0.05)." (PMID 35534796, 2022). "Another study proposed miR-215-5p function as an oncogene in gastric cancer by targeting RUNX1 tumor suppressor." (PMID 33255928, 2020). "Three target genes (EZH2, YWHAZ and RUNX1) were upregulated in gastric cancer compared to normal gastric mucosa." (PMID 30258124, 2018). "It is known that RUNX1 is expressed in gastric epithelial cells and functions as a tumor-suppressor in gastric cancer cells." (PMID 29201108, 2017). "RUNX1 functioned as a tumor suppressor in oesophagus cancer and gastric cancer, however, in oral squamous cell carcinomas and head and neck squamous cell carcinomas, RUNX1 played tumorigenic functions." (PMID 26716895, 2016). "H19 is capable of regulating the progression of gastric cancer through the H19/miR-675/runt-related transcription factor 1 (RUNX1) signaling axis." (PMID 27464701, 2016). "However, the opposite conclusion has also been reached, namely, that RUNX1 is downregulated in gastric cancer tissues, suggesting a complex role of RUNX1 in the progression of this type of cancer." (PMID 38430423, 2024). "Furthermore, the transfection of the circRNA targeting miRNA-21 was shown to impede the proliferation of gastric cancer cells by inducing apoptosis and inducing global changes in protein expression via the modulation of miR-21-5p/RUNX1 axis." (PMID 38139352, 2023). "Overexpression of RUNX1 has also been observed in hepatocellular carcinoma and gastric cancer." (PMID 35534796, 2022). "Additionally, the transcription factor RUNX1 was reported to be a target gene of miR-18a-5p, and RUNX1was directly targeted by miR-18a in gastric cancer cells." (PMID 36182925, 2022). "Studies in gastric cancer cells have shown that overexpressed circFAT1(e2) inhibits the proliferation, migration, and invasion of gastric cancer cells by targeting binding to miR-548g and releasing RUNX1." (PMID 33884267, 2021). "Additionally, elevated miR-216a-3p activates the NF-κB signaling pathway through targeting RUNX1, contributing to metastatic potential of gastric cancer." (PMID 32719745, 2020). "For example, RUNX1 was found to be downregulated in gastric cancer and hepatocellular carcinoma." (PMID 31739630, 2019). "For instance, in gastric cancer, H19-miR-675 regulates cell proliferation by repressing RUNX1." (PMID 29579063, 2018). "In gastric cancer, RUNX1 could reduce the aggressive function of miR-215, thus acting as a tumor suppressor." (PMID 29245924, 2017). "Thus H19/miR-675 regulates the expression of RUNX1 to modulate gastric cancer." (PMID 27163185, 2016). "In contrast to most reports that circFAT1 was present in cytoplasm, it was present in cytoplasm to upregulating tumor suppressor RUNX1 by acting as a sponge for miR-548g, and in nuclei to regulate YBX1 function by physical interaction in gastric cancer." (PMID 35844799, 2022). "miR-27b-3p inhibited malignant progression capacity by targeting RUNX1, Nrf2, and MARCH7 in gastric cancer, esophageal squamous cell carcinoma, and endometrial cancer, respectively." (PMID 36306007, 2022). "H19 and its mature product miR-675 enhanced the proliferation and invasion of gastric cancer AGS cells by activation of Akt/mTOR pathway, in which tumor suppressor RUNX1 served as a pivotal mediator." (PMID 27738631, 2016).
gastric cancer (continued). "For instance, this miRNA has tumor suppressor properties in many cancer types, while in gastric cancer, miR-215 has been shown to promote malignant progression by targeting the RUNX family transcription factor 1 (RUNX1) gene, which is involved in cell differentiation and apoptosis." (PMID 37175524, 2023). "In gastric cancer, FENDRR affects cell malignant activity via the miR-214-3P/TET2 axis, whereas in prostate cancer, it reduces malignancy by competitively binding miR-18a-5p with Runt-related transcription factor 1 (RUNX1)." (PMID 34621665, 2021). "Because RUNX1 is essential for the development of human hematopoietic stem cells, we proposed that PML is a potential drug target that can overcome platinum resistance in the platinum-based chemotherapy in gastric cancer." (PMID 26897165, 2016). "Additionally, Runx1 and Runx3 proteins have been shown to regulate the PI3K/Akt pathway in megakaryocytic leukemic and gastric cancer cell lines by directly affecting expression levels of p110 and Akt1 proteins, respectively." (PMID 24479521, 2014). "Consistent with RUNX1 expression patterns, significant overexpression of MUC13 was observed in various gastrointestinal cancers, such as cholangiocarcinoma, colon cancer, esophageal cancer, hepatocellular carcinoma, pancreatic cancer, rectal cancer, and gastric cancer." (PMID 39309442, 2024).